SRC (SRC proto-oncogene, non-receptor tyrosine kinase)
Diseases named in the same sentence as SRC in open-access papers (continued):
Sharing a sentence is not in itself a finding about the gene and the disease.
glioblastoma (45 papers, 2011 to 2025). The most malignant astrocytic tumor (WHO grade IV). "The aim of this work was to assess the therapeutic potential of a new targeted c-SRC inhibitor molecule, named Si306, in combination with X-rays on the human glioblastoma cell lines, comparing normoxia and hypoxia conditions." (PMID 32486205, 2020). "In this study we investigated the radiosensitive effects of a new targeted compound, SRC inhibitor, named Si306, in combination with PT on the U87 glioblastoma cell line." (PMID 31554327, 2019). "The first purpose of this study was to evaluate the radiosensitizing effects mediated by combination of the new compound, the Si306 targeting SRC proteins, with PT on the U87 human glioblastoma cell line." (PMID 31554327, 2019). "In this work we analyzed the GEP on the U87 MG human glioblastoma cell line after treatment with PT alone or in combination with a new targeted compound, named Si306 (Lead Discovery Siena, Siena, Italy), inhibiting SRC proteins." (PMID 31554327, 2019). "While first results for c-SRC targeting have been reported in the treatment of idiopathic pulmonary fibrosis, systemic sclerosis and glioblastoma, its role in liver fibrosis progression is not yet understood." (PMID 26696895, 2015). "For example, in glioblastoma, SRC could promote cholesterol imbalance through the ERK pathway." (PMID 38734640, 2024). "MerTK activates the STAT3/KRAS and SRC signaling cascades in glioblastoma multiforme (GBM)." (PMID 41195524, 2025). "YTHDF2 has been shown to contribute to glioblastoma cell proliferation and tumorigenesis, and overexpression was mediated in glioblastoma via the EGFR/SRC/ERK pathway." (PMID 37444417, 2023). "Additionally, guanylate-binding protein 5 (GBP5) promotes glioblastoma malignancy through the SRC/ERK1/2/MMP3 pathway, implicating ETS1 and MMP3 as downstream effectors of SRC signaling." (PMID 41462902, 2025). "In contrast, the EGFR/SRC/ERK signaling pathway can phosphorylate and stabilize the m6A reader protein YTHDF2, which is necessary to sustain the invasive, proliferative, and tumorigenic properties of glioblastomas." (PMID 40612868, 2025). "In glioblastoma, TLK2 overexpression correlates with poor clinical outcomes and drives cell proliferation, migration, invasion, and epithelial-mesenchymal transition through the SRC signaling pathway, while silencing TLK2 has opposite effects." (PMID 38343446, 2023). "We also discussed the link between hypoxia and radiation-induced radioresistance with activation of SRC proto-oncogene non-receptor tyrosine kinase, prospecting potential strategies to overcome the current limitation in glioblastoma treatment." (PMID 33020459, 2020). "In this review, we describe the role of the hypoxic microenvironment and SRC proto-oncogene non-receptor tyrosine kinase in the activation of radioresistance and invasion pathways of glioblastoma." (PMID 33020459, 2020). "PIK3CG, SRC, AURKA, CDK7, and PLAT might be key molecular targets of plinabulin in glioblastoma." (PMID 39877641, 2025).
gastric cancer (42 papers, 2012 to 2025). A primary or metastatic malignant neoplasm involving the stomach. "SRC rs6122566 significantly increased risk for gastric cancer in the recessive models (OR = 4.90, [95% CI 1.19–14.2])." (PMID 22383989, 2012). "SRC genetic variations that influence the cellular capacity in gastric epithelial cells are associated with gastric cancer risk." (PMID 22383989, 2012). "In the combined analysis that included the discovery and extension phases, the risk estimate of SRC rs6122566 in the recessive model was significantly associated with gastric cancer in both the pooled and meta-analyses (OR = 3.96, [95% CI: 2.05–7.65]; OR = 4.59, [95% CI: 2.74–7.70], respectively)." (PMID 22383989, 2012). "In gastric cancer, cyclase-associated protein 2 (CAP2) bound to RACK1 and activated the SRC/FAK/ERK signaling pathway, leading to IL-4 and IL10 secretion, and M2 macrophage polarization." (PMID 38315284, 2024). "SRC has been involved in the growth and metastasis of cancer cells and is also an important target for gastric cancer treatment." (PMID 38612999, 2024). "In our study, TNF, IL6, BCL2, PTEN, CTNNB1, and SRC are presented as common target genes between gastric cancer and AMK." (PMID 38612999, 2024). "In conclusion, we identified vortioxetine hydrobromide, a novel dual JAK2/SRC inhibitor, inhibited gastric cancer cell proliferation, through reducing STAT3 dimerization and nuclear translocation in vivo and in vitro." (PMID 37147297, 2023). "In this study, we found that vortioxetine hydrobromide is a dual JAK2/SRC inhibitor and suppresses the growth of gastric cancer cells in vivo and in vitro." (PMID 37147297, 2023). "JAK2 and SRC have emerged as important therapeutic targets for several cancers including head and neck squamous cell carcinoma, breast cancer, lung cancer and gastric cancer." (PMID 37147297, 2023). "In this study, we find that vortioxetine hydrobromide, an FDA-approved drug, is a dual JAK2/SRC inhibitor, and has inhibitory effects on cell proliferation of gastric cancer." (PMID 37147297, 2023). "SRC plays an important role in the migration of gastric cancer cells by mediating a potential CXCR4-EGFR crosstalk and sequentially activating the EGFR-Akt/ERK axis." (PMID 36299773, 2022). "Polyunsaturated fatty acid biosynthesis modulates gastric cancer cell ferroptosis, which is blocked by α6β4/SRC/STAT3-mediated inhibition of ACSL4 (acyl-coA synthetase long-chain family member 4)." (PMID 36289191, 2022). "The elevated SRC activity in gastric cancer (GC) has prompted the need for the therapeutic application of dasatinib in GC." (PMID 33291786, 2020). "It has been shown that knockdown of endogenous DARPP-32 increases TRAIL-induced apoptosis in gastric cancer cell lines through activation of SRC/STAT3 signalling, which contributed to our rationale for selecting TRAIL as an inducer of apoptosis." (PMID 32499571, 2020). "We found that reduced SRC and LYN methylation and increased CKB methylation was associated with gastric cancer." (PMID 26460485, 2015). "This study shows SRC, c-MET, and CRK genetic variants can be susceptible genetic factors for the development of gastric cancer by controlling signals through the CagA transduction pathways." (PMID 22383989, 2012). "Because some CagA interacting molecules such as SHP-2, CRK and CSK are only able to respond with phosphorylated CagA, SRC can be more important in influencing other's cellular functions and inducing development of gastric cancer." (PMID 22383989, 2012). "c-SRC was the first oncogene discovered and has increased expression in gastric cancer." (PMID 38612999, 2024). "Furthermore, vortioxetine hydrobromide inhibits the cell proliferation dependent on JAK2 and SRC and suppresses the growth of gastric cancer PDX model in vivo." (PMID 37147297, 2023).
gastric cancer (continued). "Moreover, a newly published study using gene-set enrichment analysis (GSEA) reported that in gastric cancer patients, GGT was significantly associated with EMT, KRAS, SRC and PKCA signaling pathways, which are involved in cancer progression and metastasis." (PMID 31664937, 2019). "In the extension phase, two SNPs, rs6122566 and rs6124914, in SRC gene and rs7208768 in CRK remained significantly associated with an increased risk for gastric cancer (OR = 4.01, [95% CI: 1.62–9.96]; OR = 1.30, [95% CI: 1.00–1.70]; OR = 1.33, [95% CI: 1.08–1.64], respectively)." (PMID 22383989, 2012). "To evaluate this hypothesis, we genotyped 137 SNPs in seven candidate genes and demonstrated that genetic variants of SRC (rs6122566 and rs6124914), c-MET (rs41739) and CRK (rs7208768) were significantly associated with gastric cancer risk." (PMID 22383989, 2012). "Our findings suggest that SRC, c-MET and CRK play a key role in gastric carcinogenesis by modulating CagA signal transductions and interaction between CRK gene and phytoestrogens modify gastric cancer risk." (PMID 22383989, 2012). "Though additional stratified analyses were also conducted to detect an interaction between CagA seropositivity and each gene effect for gastric cancer risk, interactions were not significant in any of the three genes, SRC, c-MET and CRK (data not shown)." (PMID 22383989, 2012). "The genes targeted by AMK in the context of gastric cancer include apoptosis regulator Bcl-2 (BCL2), catenin beta 1 (CTNNB1), B-cell stimulatory factor 2 (IL6), mutated in multiple advanced cancers 1 (PTEN), proto-oncogene (SRC), and tumor necrosis factor ligand member 2 (TNF)." (PMID 38612999, 2024). "It was recently found that OSM promotes the proliferation, migration, and invasion of gastric cancer cells and that OSM and OSM receptor contribute to GC progression by activating STAT3/FAK/SRC signaling." (PMID 31871447, 2019). "These hub genes such as SRC (Proto-Oncogene C-Src), DNM1L (Dynamin 1-Like) and POLR1C (polymerase (RNA) I polypeptide C) are critical downstream effectors of CEACAM6 in gastric cancer progression." (PMID 29137373, 2017). "In this study, we aimed to evaluate SRC, LYN and CKB protein and mRNA expression, as well as their promoter methylation, in gastric cancer." (PMID 26460485, 2015). "Expression of SRC, LYN and CKB in gastric cancer is significantly associated with tumor invasion and lymph node and distant metastases, as well as with MYC expression, which is also a possible biomarker for GC." (PMID 26460485, 2015). "EMT, KRAS, SRC and PKCA pathways may be the key signaling pathways in the GGT signaling in gastric cancer." (PMID 28404903, 2017). "Moreover, SRC rs6124914, c-MET rs41739 and CRK rs7208768 showed significant gene-dose effects for gastric cancer in both analyses." (PMID 22383989, 2012). "Furthermore, in gastric cancer cells, VPS35 expression is upregulated, and it positively regulates the proliferation and peritoneal metastasis of gastric cancer cells through integrin/FAK/SRC signalling-mediated IL-6/STAT3 pathway activation in a YAP-dependent manner." (PMID 40484931, 2025). "Similar to SRC, FYN is an SFK that is overexpressed in GC and is positively correlated with metastasis and may promote gastric cancer metastasis by activating STAT3-mediated epithelial-mesenchymal transition." (PMID 33479376, 2021). "In order to assess the relevance of these five kinases in gastric cancer tumors, we analysed the mRNA and protein levels in 200 biopsies from gastric cancer patients, revealing that transcript and protein levels of FRK, DDR1, SRC were elevated in metastatic tissues regardless of tumor stage." (PMID 32082487, 2020).
glioma (42 papers, 2010 to 2026). A benign or malignant brain and spinal cord tumor that arises from glial cells (astrocytes, oligodendrocytes, ependymal cells). "CD90 is a specific surface marker highly expressed in glioma-associated mesenchymal stem cells and drives glioma progression through SRC-dependent mechanisms increasing proliferation, migration, and adhesion." (PMID 33155039, 2020). "In the subnetworks, several kinases, such as ABL1, ACVR1, EPHA4, MAPK9, PAK1 and SRC, were commonly associated with glioma, cell migration and cell death/survival." (PMID 32392905, 2020). "Network pharmacology and molecular docking analyses have identified EGFR and SRC as direct molecular targets of Kae in glioma therapy." (PMID 41009025, 2025). "In these “phospho-SFK high” tumours 66% also expressed high PDGFRA or PDGFRB or both, supporting a scenario in which PDGFR signalling contributes to SRC/SFK activation in high-grade gliomas." (PMID 33478100, 2021). "CD44, a hyaluronic acid receptor that associates and promotes c-SRC activation and is involved in glioma cell invasion, was upregulated in almost all foci and correlated with c-SRC activation." (PMID 32680567, 2020). "Wei and colleagues have recently reported that the CD133/PI3K/Akt signaling axis regulates glioma stem cell behavior, self-renewal, and tumorigenesis, as SRC binds to the cytoplasmic tail of CD133 and consequently activates the PI3K/Akt pathway." (PMID 24468059, 2014). "The biological function of SH2B3 by which it promotes glioma initiation and progression may rely on binding with SRC homology domain." (PMID 33937225, 2021). "NLGN3 promotes glioma cell proliferation by activating multiple oncogenic signaling pathways, including PI3K-mTOR, SRC, and RAS, offering a novel perspective on the integration of gliomas with neural circuits." (PMID 40092993, 2025). "The combination of Kae and Gef (gefitinib) results in a more pronounced inhibition of glioma cell proliferation compared to either treatment alone, and Kae further enhances the inhibition of EGFR and SRC phosphorylation when used alongside Gef." (PMID 41009025, 2025). "Key findings in glioma patients in relation to m6A ‘readers’ include YTHDF2 overexpression, induced through the EGFR/SRC/ERK pathway to promote tumourigenesis, invasiveness, and cell proliferation independently associated with poor prognosis." (PMID 36831575, 2023). "In glioma cells, CD155 mediates adhesion to the extracellular matrix protein vitronectin, promotes FA turnover and FA signaling towards SRC, paxillin, and p130CAS, and thereby contributes to tissue invasion." (PMID 35296518, 2022). "Inhibiting SRC and upregulating PTEN significantly reduces the migration and invasion of glioma stem cells, leading to a growing interest in developing novel SRC inhibitors for glioma treatment." (PMID 37865727, 2023). "Whereas the LG DI tumor showed common glioma changes, such as EGFR upregulation, and ERK/MAPK and CD44/c-SRC pathway activation, the latter involved in glioma cell invasion, the HG LM component lacked these changes." (PMID 33853673, 2021). "Because SRC and PDGF are key upstream mediators of PI3K/Akt signaling pathway, and has been shown to have important roles in cell proliferation, migration and survival, we hypothesized that Akt activation might contribute to CCR10 mediated proliferation and invasion in glioma." (PMID 25149529, 2014).
osteosarcoma (34 papers, 2011 to 2025). A usually aggressive malignant bone-forming mesenchymal neoplasm, predominantly affecting adolescents and young adults. "In addition, the protein encoded by SRC is a non‐receptor tyrosine kinase protein that involves in various intracellular signaling transduction related to osteosarcoma." (PMID 38086608, 2024). "According to the expected core targets of the PPI network that were significantly associated with anti-osteosarcoma effects, the top five target proteins (EGFR, Caspase-3, ESR1, HSP90AA1, and SRC) ranked by degree value were subjected to molecular docking." (PMID 40991530, 2025). "Among these core targets, EGFR (48-sided), CASP3 (47-sided), ESR1 (42-sided), HSP90AA1 (42-sided), SRC (42-sided) and IGF1 (40-sided) have high nodes, indicating that they are closely associated with PA anti-osteosarcoma dense mechanisms." (PMID 40991530, 2025). "EphA2 silencing was consistently associated with reduced activating phosphorylation of AKT, ERK1/ERK2, and SRC kinases in both human and canine osteosarcoma cells." (PMID 39056783, 2024). "SPON1 upregulation is closely related to metastasis and progression of osteosarcoma, promoting migration and invasion of osteosarcoma cells in vivo and in vitro, as well as activating FAK (PTK2) and SRC in osteosarcoma cells." (PMID 36520032, 2023). "The SLIT2/ROBO1 axis contributes to the Warburg effect by activating the SRC/ERK/c-MYC/PFKFB2 pathway in osteosarcoma." (PMID 37197432, 2023). "Aspergillus niger inhibits osteosarcoma cell growth and induces apoptosis by inhibiting the SRC/STAT3 signaling pathway in osteosarcoma." (PMID 36291659, 2022). "Studies have also found that the SLIT2/ROBO1 axis promotes the Warburg effect of osteosarcoma by activating the SRC/ERK/c-MYC/PFKFB2 pathway." (PMID 36387908, 2022). "For example, the bone osteosarcoma cell line U2OS is sensitive to the SRC/ABL dual inhibitor saracatinib even when the target gene SRC is knocked down." (PMID 34924565, 2021). "PPI results showed that EGFR, CASP3, ESR1, HSP90AA1, and SRC may be potential targets for PA against osteosarcoma." (PMID 40991530, 2025). "Additionally, PHLDA2 has been shown to impact EMT and metastasis in osteosarcoma through the SRC/PI3K/AKT/mTOR and WNT/GSK3-β/β-catenin signaling pathway." (PMID 38827322, 2024). "After treating osteosarcoma cells with cisplatin, a widely used anticancer drug, it induces the overexpression of GFRα1, which promotes autophagy to lead to enhanced osteosarcoma cell survival via the SRC-AMPK signaling axis." (PMID 35582425, 2022). "Similarly, the highly potent pan-SFK inhibitor A-770041 and/or short hairpin RNAs (shRNAs) against SRC mRNA reduced c-Src expression in osteosarcoma cell lines and enhanced their sensitivity to doxorubicin or paclitaxel." (PMID 32517369, 2020). "And migration and invasion of human osteosarcoma cells could be inhibited by targeting SRC." (PMID 38086608, 2024). "Our findings reveal that troxerutin effectively inhibits CD155, attenuates the SRC/AKT/GSK3β signaling cascade, diminishes the nuclear localization of β-catenin, and consequently mitigates osteosarcoma stemness." (PMID 40217455, 2025). "For instance, inhibition of the SRC/STAT3 signaling pathway by ameloblastin was shown to induce apoptosis and suppress chemoresistance of osteosarcoma cells." (PMID 38086608, 2024). "GFRA1 expression promotes autophagy by activating the SRC-AMPK signaling axis following cisplatin treatment, resulting in enhanced osteosarcoma cell survival." (PMID 29617307, 2018). "Dasatinib (BMS-354825, Sprycel), a SRC TKI, is currently used in the treatment of chronic myeloid leukemia and is in clinical trials for osteosarcoma, NSCLC, and other cancers." (PMID 25501935, 2014).
osteosarcoma (continued). "Advanced molecular techniques, such as RNA sequencing and co-immunoprecipitation, have been instrumental in elucidating the mechanism of CD155 in activating the Wnt/β-catenin pathway via the SRC/AKT/GSK3β signaling axis, thereby enhancing the stem-cell-like properties of osteosarcoma cells." (PMID 40217455, 2025). "Inhibiting SRC activated by TGF-β1 impaired the activation of ERK, Smad2, and Smad3, as well as Smad nuclear translocation, which, in turn, inhibited the induction of CTGF in rat osteosarcoma osteoblast-like cells." (PMID 38167009, 2024). "Eight out of the 54 hub‐genes (ASPM, CENPF, KIF14, KIF20A, RCC1, SMC2, SRC, and TOP2A) were significantly decreased after NACT (criteria: |fold change| ≥ 2 and adjusted p value < 0.05), consistent with the central role of these hub genes in osteosarcoma." (PMID 37457661, 2023).